NOD2 (nucleotide binding oligomerization domain containing 2)
Diseases named in the same sentence as NOD2 in open-access papers (continued):
Sharing a sentence is not in itself a finding about the gene and the disease.
Atherosclerotic lesion (1 paper, 2007). A lesion associated with atherosclerosis, a multifactorial and multipart progressive disease manifested by the focal development within the arterial wall of lesions, that ranges from the development of a fatty streak, plaque progression, and plaque disruption. "In this study, we demonstrated that NOD2 is mainly expressed in macrophages in coronary artery lesions, suggesting that NOD2 might modulate the local immune response and infection control in atherosclerotic lesions." (PMID 17980027, 2007).
autoimmune hepatitis (1 paper, 2022). Hepatitis caused by autoantibodies. "NOD2-deficient mice were resistant to the induction of autoimmune hepatitis (AIH) induced by concanavalin A (ConA) compared to the susceptibility of NOD2-intact mice, and this resistance was associated with reduced expression of IFN-γ-in the liver." (PMID 36268029, 2022).
bacteremia (1 paper, 2013). "Results from two studies involving critically-ill sepsis patients suggest an increased risk of bacteremia and mortality in individuals with at least one NOD2 variant." (PMID 24086711, 2013).
basal cell carcinoma (1 paper, 2022). A carcinoma involving the basal cells. "Genes in the low-expression cohorts of CD14, CYBB, NOD2, and TLR1 were all highly enriched in olfactory transduction, linoleic acid metabolism, and basal cell carcinoma." (PMID 36193326, 2022).
Bovine mastitis (1 paper, 2022). INFLAMMATION of the UDDER in cows. "Our data suggest that genes TLR4, NOD2, CXCL8, and OAS2 are key components involved in the host immune response to bovine mastitis and that the lncRNAs MSTRG25101.2, MSTRG.56327.1, and MSTRG.18968.1 adjacent to the SCC QTL and SCS QTL may potentially regulate expression of these candidate genes." (PMID 36204322, 2022).
brain injury (1 paper, 2023). Acute and chronic (see also brain INJURIES, CHRONIC) injuries to the brain, including the cerebral hemispheres, CEREBELLUM, and brain STEM. "This study demonstrates that NBP maintains BBB function by activating the Nrf2/HO-1 pathway and inhibiting the NOD2/MAPK/NF-κB pathway to suppress inflammation and oxidative stress, thereby alleviating renal I/R-induced brain injury." (PMID 37732403, 2023).
Cachexia (1 paper, 2023). Severe weight loss, wasting of muscle, loss of appetite, and general debility related to a chronic disease. "We also observed that Caspase 1 gene expression increased in terminal cachexia, whereas Nod2 gene expression was increased only on T7, returning to basal levels in T14, whereas Nod1 and Hif‐1α gene expression did not change during the development of cachexia." (PMID 37177862, 2023).
Camptodactyly (1 paper, 2024). The distal interphalangeal joint and/or the proximal interphalangeal joint of the fingers or toes cannot be extended to 180 degrees by either active or passive extension. "All five heterozygous carriers of c.1412G>C in NOD2 had camptodactyly." (PMID 38927735, 2024).
Candida infections (1 paper, 2019). "NOD2 polymorphisms were not increased in patients with Candida infections and Candida-induced cytokine responses were unaffected in patients with NOD2 polymorphisms." (PMID 29522806, 2019).
Carditis (1 paper, 2011). "We also examined the effect of the Nod2 deficiency on carditis in response to B. burgdorferi." (PMID 21387014, 2011).
Chagas disease (1 paper, 2020). A parasitic infection caused by Trypanosoma cruzi. "cruzi isolated from a patient with a digestive form of Chagas Disease in a previously work was inoculated in NOD2-deficient mice in an attempt to reproduce gastrointestinal changes observed in Chagas`patients with digestive clinical form." (PMID 32986710, 2020). "Together, our results indicate that deficiency in NOD2 expression associated to T. cruzi strain that causes persistent intestinal inflammation promotes the breakdown of homeostasis of the digestive system, making patients more susceptible to the development of the digestive form of Chagas’ disease." (PMID 32986710, 2020). "We observed here that patients with digestive and cardiodigestive forms of Chagas’ disease present absence or reduced NOD2 mRNA expression." (PMID 32986710, 2020). "The aim of this work was to evaluate the role of NOD2 innate immune receptor in the pathogenesis of the digestive system in Chagas’ disease." (PMID 32986710, 2020). "Together, our results suggest that NOD2 plays a protective role against the development of digestive form of Chagas’ disease." (PMID 32986710, 2020). "Finally, NOD2 is a protective factor against the development of digestive form of Chagas’ disease by impacting in the control of parasite-induced inflammation and microbiota homeostasis." (PMID 32986710, 2020). "In order to confirm the importance of the NOD2 receptor in the genesis of digestive tract lesions in Chagas’ disease, the development of gastrointestinal tract lesions was evaluated in NOD2 knockout mice infected with T. cruzi obtained from a digestive patient." (PMID 32986710, 2020). "Here we showed that patients with digestive form of Chagas’ disease do not express the innate immune receptor NOD2." (PMID 32986710, 2020).
cholangitis (1 paper, 2017). An acute or chronic inflammatory process affecting the biliary tract. "Analysis of Cohort 1 revealed that four of the five patients with NOD2 variants had multiple recurrent episodes of cholangitis whereas this was seen in only 33.3% of the NOD2 wild-type patients." (PMID 28765628, 2017).
cholestasis (1 paper, 2024). Impairment of the bile flow caused by obstruction within the liver, or outside the liver in the bile duct system. "NOD2-deficient mice are protected from cholestasis-induced liver injury and fibrosis." (PMID 38343546, 2024).
cholesteatoma (1 paper, 2015). A pathologic process characterized by the proliferation of keratinizing squamous epithelium resulting in the accumulation of keratin and cells in the middle ear and/or mastoid. "It is also important to note that elements of the ERBB2IP signaling network, which is known to be associated with NOD2 signaling, were found to be downregulated in cholesteatoma compared to EAS." (PMID 25922834, 2015). "Real-time PCR (QPCR) data indicated that the mRNA expression of NOD2 was significantly increased in cholesteatoma compared to EAS." (PMID 25922834, 2015). "Immunohistochemistry demonstrated that, while only NOD2 was enhanced in cholesteatoma compared to EAS, both NOD1 and NOD2 are present in cholesteatoma." (PMID 25922834, 2015). "The role of NLR signaling on cholesteatoma has not been well studied, although a recent study documented enhanced levels of NOD2 mRNA." (PMID 25922834, 2015). "Indeed, we found a significantly robust upregulation of the proinflammatory-related genes TNFα, IL1β, IRAK1, p65, NOD2, and a downregulation of IKK2 in cholesteatoma." (PMID 25922834, 2015). "Thus, the nature of NLR signaling in cholesteatoma, with enhancement of NOD2 but not NOD1 expression, may contribute to the progressive and invasive nature of this disease." (PMID 25922834, 2015). "Microarray analysis showed significant upregulation for NOD2, not for NOD1, TLR2, or TLR4 in cholesteatoma." (PMID 25922834, 2015).
diabetic foot ulcers (1 paper, 2025). "The expression of NOD2 is significantly increased in patients with diabetic foot ulcers, and the activation of NOD2 will further aggravate the inflammatory response and inhibit the migration and proliferation of keratinocytes, thereby delaying healing." (PMID 40666801, 2025).
dry eye (1 paper, 2021). "In dry eye, NOD2 can induce increased production of inflammatory cytokines and T cells on the ocular surface by upregulating RIP2 and NF-κB, resulting in corneal epithelial apoptosis and damage." (PMID 33670592, 2021). "We have reported that NOD2 signaling is involved in the pathogenesis of dry eye and aggravates clinical and experimental parameters." (PMID 33670592, 2021).
dysautonomia (1 paper, 2024). An acute or chronic disorder, affecting the sympathetic or parasympathetic nervous system. "It is uncertain whether gastrointestinal dysmotility, dysautonomia (e.g., POTS, orthostasis), and mast cell activation disorder are comorbidities or mechanistically related to NOD2 variants or the diagnosis of YAOS." (PMID 39430755, 2024).
dysplasia (1 paper, 2020). A usually neoplastic transformation of the cell, associated with altered architectural tissue patterns. "Moreover, NOD2 or RIP2 deficiency resulted in a pro-inflammatory microenvironment that enhanced epithelial dysplasia following chemical injury and causes gut dysbiosis probably due to higher abundance of Rikenella bacterium in these mice." (PMID 32999308, 2020).
endometritis (1 paper, 2021). An acute or chronic, usually bacterial infectious process affecting the endometrium. "We found NLRC4−/− and AIM2−/−, NOD1−/−, NOD2−/−, and GBPchr3−/− mice developed severe endometritis at day 56 pi." (PMID 34526512, 2021).
endothelial dysfunction (1 paper, 2018). In vascular diseases, endothelial dysfunction is a systemic pathological state of the endothelium (the inner lining of blood vessels) and can be broadly defined as an imbalance between vasodilating and vasoconstricting substances produced by (or acting on) the endothelium. "New therapies targeting NOD2/MEK/ERK pathway is a promising strategy to treat DN endothelial dysfunction and reduce inflammation." (PMID 30741617, 2018).
esophageal cancer (1 paper, 2023). A primary or metastatic malignant neoplasm involving the esophagus. "The abnormal low expression of NOD2 in esophageal cancer might also be one of the factors that causes the disease, but the factors causing the decrease in NOD2 expression are still unclear." (PMID 36316517, 2023).
filariasis (1 paper, 2022). "Wolbachia can also be recognized by the nucleotide-binding oligomerization domain-containing protein 2 (NOD2), which supports neutrophil recruitment to the skin and subsequent L3 larval elimination in murine filariasis." (PMID 36389745, 2022).
glomerulosclerosis (1 paper, 2017). A hardening of the kidney glomerulus caused by scarring of the blood vessels. "On the other hand, overexpression of Nod2, also related to “sterile inflammation”, was first observed only 60 days after Nx, when glomerulosclerosis was already significant." (PMID 28600543, 2017).
gram-negative pneumonia (1 paper, 2015). "While previous studies found a role for NOD2 in host defense against gram-negative pneumonia, limited data exists on the involvement of NOD2 in host defense in gram-positive pneumonia." (PMID 26673231, 2015).
gram-positive bacterial infections (1 paper, 2013). Infections caused by bacteria that retain the crystal violet stain (positive) when treated by the gram-staining method. "NOD2 is also involved in modulation of Toll-like receptor (TLR) signaling, and regarding this latter the recipient TLR2 R753Q variant has also been associated with presentation with septic shock and infection recurrence with gram-positive bacterial infections after OLT." (PMID 23977330, 2013).
Hyperbilirubinemia (1 paper, 2014). An increased amount of bilirubin in the blood. "Genetic analysis of the frequency of minor allele of NOD2, CARD9, RAC1 and ATG16L1 polymorphisms in IF patients with conjugated hyperbilirubinemia (CB≥50 μmol/L)." (PMID 24465786, 2014). "Genetic analysis of the frequency of minor allele of NOD2, CARD9, RAC1 and ATG16L1 polymorphisms in IF patients with conjugated hyperbilirubinemia (CB≥100 μmol/L)." (PMID 24465786, 2014).
hypertensive disorder (1 paper, 2022). Persistently high systemic arterial blood pressure. "Furthermore, common TLR4 and NOD2 gene variants alter the maternal inflammatory responses, which damage the inflammatory response to endotoxin, and are associated with severe hypertensive disorders in pregnancy." (PMID 36496806, 2022).
inflammatory bowel disease 1 (1 paper, 2020). Any inflammatory bowel disease in which the cause of the disease is a mutation in the NOD2 gene. "The hormone-bound VDR regulates the expression of multiple human CD susceptibility loci, including the pattern recognition receptor NOD2, also known as IBD1 (inflammatory bowel disease 1)." (PMID 32349265, 2020).
injury (1 paper, 2022). Damage inflicted on the body as the direct or indirect result of an external force, with or without disruption of structural continuity. "In corneal injury mice caused by blue light stimulation, the ROS-NOD2-ATG16L1 signaling pathway might be participated in autophagy induction with the excessive expression of NOD2 on the ocular surface, which leads to corneal epithelial cell apoptosis and death." (PMID 35505403, 2022).
intestinal infections (1 paper, 2025). "In their paper, Sue hypothesized that susceptibility to more severe intestinal infections in some full-term infants may be linked to variations in Toll-like receptors (TLR-2, TLR-4) and nucleotide-binding oligomerization domain-containing protein 2 (NOD2) or in genes encoding similar proteins." (PMID 40284610, 2025).
invasive breast carcinoma (1 paper, 2020). A carcinoma that infiltrates the breast parenchyma. "The co-expression profile of PITX1 was identified with a large cluster of 12,624 measured genes across 103 invasive breast carcinomas, the nucleotide-binding oligomerization domain 2 (NOD2) is a principal co-expression gene." (PMID 32830857, 2020).
keratitis (1 paper, 2024). A corneal disease that is characterized by inflammation of the cornea. "Moreover, in a keratitis model it has been reported that TLR-2 – NOD2 synergism provides an enhanced inflammatory cytokine response to conidia." (PMID 39605324, 2024).
leishmaniasis (1 paper, 2023). Infectious disease that is transmitted through the bite of hematophagous female phlebotomine sand flies. "We investigated whether variants in the NOD2 gene (R702W rs2066844, G908R rs2066845, and L1007fsinsC rs2066847) are associated with susceptibility to CL caused by L. guyanensis (Lg) in 837 patients with Lg-Cl and 797 healthy controls (HC) with no history of leishmaniasis." (PMID 36795715, 2023).
lepromatous leprosy (1 paper, 2021). A chronic communicable infection which is a principal or polar form of leprosy. "Likewise, a NOD-2 defect is also associated with an increased susceptibility to lepromatous leprosy." (PMID 33957980, 2021).
lupus nephritis (1 paper, 2019). Glomerulonephritis in the context of systemic lupus erythematosus. "The expression of NOD2, NLRP3 and NLRC5 was significantly higher in kidneys from AAV patients than those from normal controls, minimal change disease or class IV lupus nephritis." (PMID 31186034, 2019).
malaria (1 paper, 2021). Malaria is a serious and sometimes fatal disease caused by a parasite that commonly infects a certain type of mosquito which feeds on humans. "In particular, the malaria pigment, haemozoin, which is also present in GCT, is a potent pro-inflammatory stimulus for macrophages, leading to the activation of the toll-like receptors, inflammasome complex, and NOD2 pathway." (PMID 33568138, 2021).
meningococcal infection (1 paper, 2013). Infections with bacteria of the species neisseria meningitidis. "Both the human and mice data indicate that NOD2 represents an important component in the generation of damaging CNS inflammation following meningococcal infection." (PMID 23691182, 2013).
metastatic tumours (1 paper, 2021). "Surprisingly, among all the 13 PDEIRGs, only NOD2 had a positive correlation with tumour stage: descended NOD2 expressions were found in larger primary tumours, metastatic tumours and advanced tumours." (PMID 34268854, 2021).
middle ear infection (1 paper, 2014). "Since we demonstrated a potent antimicrobial effect of human β-defensin 2 on NTHi, we sought to determine if NOD2 deficiency influences the pathogenesis of middle ear infection." (PMID 24625812, 2014).
Multiple Organ Failure (1 paper, 2025). A progressive condition usually characterized by combined failure of several organs such as the lungs, liver, kidney, along with some clotting mechanisms, usually postinjury or postoperative. "IL17A, IL1B, MBL, and NOD2 were also reported to be associated with mortality, and PPARG was associated with multiple organ failure in our study." (PMID 40168842, 2025).
myocardial infarction (1 paper, 2018). Gross necrosis of the myocardium, as a result of interruption of the blood supply to the area, as in coronary thrombosis. "Consistent with our findings, NOD2 knockout was protective against myocardial infarction." (PMID 29940016, 2018).
nasal polyps (1 paper, 2012). "Relevant to our finding of NRLP3 in the normal mouse bronchiolar epithelium is the recent observation reporting NRLP3 and two other NLRs (NOD1 and NOD2) in upper airway human tissues including normal nasal mucosa, nasal polyps, tonsils, and adenoids." (PMID 22523501, 2012).
osteonecrosis (1 paper, 2022). A none disease characterized by death of bone tissue due to a lack of blood supply. "Our study indicated that hsa-miR-320a was a key regulator of NOD2 associated with inflammation contributing to the progression of osteonecrosis." (PMID 36193326, 2022). "Furthermore, miRNAs and TFs targeting CD14, CYBB, NOD2, and TLR1 were predicted and a total of 20 differentially expressed miRNAs were identified in patients with osteonecrosis and controls." (PMID 36193326, 2022).
ovarian endometriosis (1 paper, 2024). A non-neoplastic disorder characterized by the growth of endometrial tissue in the ovaries. "In this study, we aim to investigate inflammasome regulators PYDC1 and PYDC2 and genetic variations in the NOD1 and NOD2 genes in patients with ovarian endometriosis." (PMID 40034240, 2024).
periapical periodontitis (1 paper, 2022). Inflammation of the periapical tissue. "Hepcidin has an important role in iron metabolism affecting bone metabolism.We investigated the role of nucleotide binding oligomerization domain containing 2 and hepcidin in inflammatory periapical periodontitis." (PMID 35764993, 2022). "Immunohistochemistry showed increased expressionof nucleotide binding oligomerization domain containing 2 and hepcidin around root apices in rats of the periapical periodontitis group." (PMID 35764993, 2022).
pertussis (1 paper, 2017). A contagious bacterial respiratory infection caused by Bordetella pertussis. "In addition, we observed an increased activation of TLR2 and NOD2 by strains circulating after, compared to before, the introduction of the pertussis vaccines." (PMID 28076445, 2017). "Furthermore, we observed a significant increase in TLR2 and NOD2, but not TLR4, activation by strains circulating after the introduction of pertussis vaccines." (PMID 28076445, 2017).
PFAPA syndrome (1 paper, 2015). An auto inflammatory syndrome characterized by recurrent febrile episodes associated with aphthous stomatitis, pharyngitis and cervical adenitis. "Recent study on predominant mutations in MEFV, CARD15/NOD2, TNFr1A, and NLRP3 genes in patients diagnosed with PFAPA syndrome showed that 19 of 57 patients carried one or more of the variants tested, with MEFV gene variants being found in 16 patients." (PMID 25821352, 2015).
pharyngeal squamous cell carcinoma (1 paper, 2016). A squamous cell carcinoma that arises from the pharynx. "A previous study demonstrated that the pharyngeal squamous cell carcinoma cell lines Detroit-562 cells showed prominent expression of NOD1, and FaDu cells exhibited presence of foremost NOD1, but expressed less NOD2 than did healthy primary human nasal epithelial cells." (PMID 27557518, 2016).
renal dysfunction (1 paper, 2020). "We found that the NOD2/CARD15 variant decreased the risk of renal dysfunction in MM patients (OR = 0.23, 95% CI 0.07-0.74, p = 0.009)." (PMID 32596371, 2020). "The presence of NOD2/CARD15 3020insC decreased the risk of renal dysfunction in MM (OR = 0.23, 95% CI 0.07-0.74, p = 0.009)." (PMID 32596371, 2020).